PSME3IP1 (proteasome activator subunit 3 interacting protein 1)
Description:
Promotes the association of the proteasome activator complex subunit PSME3 with the 20S proteasome and regulates its activity. Inhibits PSME3-mediated degradation of some proteasome substrates, probably by affecting their diffusion rate into the catalytic chamber of the proteasome. Also inhibits the interaction of PSME3 with COIL, inhibits accumulation of PSME3 in Cajal bodies and positively regulates the number of Cajal bodies in the nucleus.
Synonyms: C16orf94; FAM192A; NIP30; PIP30; CDA018; CDA10
Tractability: Small molecule: a structure with a bound ligand is known. PROTAC: ubiquitination databases record sites on it.
Gene: Protein-coding gene on chromosome 16 (57,152,466 to 57,186,175, reverse strand). Ensembl gene ENSG00000172775.
Subcellular location: Nucleus
Subcellular location (Human Protein Atlas): Nucleoplasm; Vesicles
Gene Ontology:
Molecular function: protein binding
Biological process: negative regulation of proteasomal protein catabolic process; negative regulation of protein binding; mRNA splicing, via spliceosome
Cellular component: nucleoplasm; nucleus; spliceosomal complex; U2-type catalytic step 1 spliceosome
Genetic constraint (gnomAD): Loss-of-function variants: 13 observed, 30.55 expected, observed/expected ratio (o/e) 0.43, 90% interval 0.28 to 0.68. The upper end of that interval is the gene's LOEUF score, 0.68, which puts it in group 2 of 6, group 1 being the genes least tolerant of losing a copy. Missense variants: 231 observed, 302.69 expected, observed/expected ratio (o/e) 0.76, 90% interval 0.69 to 0.85. Synonymous variants: 91 observed, 116.24 expected, observed/expected ratio (o/e) 0.78, 90% interval 0.66 to 0.93.
Homologues: Orthologues: chimpanzee PSME3IP1 (99% identical), macaque PSME3IP1 (99% identical), guinea pig Psme3ip1 (96% identical), pig PSME3IP1 (96% identical), dog PSME3IP1 (94% identical), mouse Psme3ip1 (93% identical), rat Psme3ip1 (93% identical), rabbit PSME3IP1 (90% identical), tropical clawed frog psme3ip1 (61% identical), zebrafish psme3ip1 (56% identical), Drosophila melanogaster CG14480 (38% identical), Caenorhabditis elegans C25A1.1 (31% identical).
Diseases named in the same sentence as PSME3IP1 in open-access papers:
PSME3IP1 is named in the same sentence as 4 diseases in open-access papers, as found by Europe PMC text mining. Sharing a sentence is not in itself a finding about the gene and the disease.
PSME3IP1 shares sentences with these, for which no sentence is quoted: cancer (1 paper); osteoporosis (1); tumor (1); viral infection (1).